CXCL1 (C-X-C motif chemokine ligand 1)
Diseases named in the same sentence as CXCL1 in open-access papers (continued):
Sharing a sentence is not in itself a finding about the gene and the disease.
cutaneous leishmaniasis (1 paper, 2021). Leishmaniasis affecting the skin. "RANTES/CCL5, together with KC/CXCL1 and MIP-2/CXCL2 participate in neutrophil, monocyte, and lymphocyte recruitment to inflammatory focus and interfere in the persistence of cutaneous leishmaniasis lesions." (PMID 34178725, 2021).
cystic fibrosis (1 paper, 2023). Autosomal recessive disorder caused by pathogenic variants in the CFTR gene (cystic fibrosis transmembrane conductance regulator), which encodes a chloride and bicarbonate channel expressed in epithelial cells, and follow the diagnosis criteria. "These cells are also identified as major recruiters of neutrophils in cystic fibrosis through CXCL1 production." (PMID 37445635, 2023). "Alveolar macrophages recruit and stimulate neutrophils by secreting granulocyte-colony stimulating factor (G-CSF), IL-6, and CXCL1 in mouse models of allergic airway disease and other lung disease models, such as cystic fibrosis." (PMID 37445635, 2023).
dengue (1 paper, 2020). "Further assessment of host factors revealed that cytokines such as CCL2, CCL5, CCL20 and CXCL1, as well as adhesion molecule ICAM-1, that are involved in leukocytes infiltration were expressed higher in dengue patients in comparison to healthy individuals." (PMID 32764789, 2020).
diabetic eye disease (1 paper, 2024). A group of disorders affecting the eye in patients with diabetes mellitus. "However, concentrations of chemokines (CCL3, CCL9 and CXCL1) retained no significance alone and concentrations of chemokines (CCL5 and CXCL4) were lower in the diabetic eye disease patients than in the controls." (PMID 38790059, 2024).
diabetic neuropathy (1 paper, 2015). A chronic, pathological complication associated with diabetes mellitus, where nerve damages are incurred due to diabetic microvascular injury involving small blood vessels that supply these nerves, resulting in peripheral and/or autonomic nerve dysfunction. "It was also reported that, in patients with diabetic neuropathy, the serum level of CXCL1 is higher than in healthy people." (PMID 25789329, 2015). "The results of our studies suggest an important role for CXCL1, CXCL5, CXCL9, and CXCL12 in STZ-induced diabetic neuropathy." (PMID 25789329, 2015). "This study verifies that, in streptozotocin-induced diabetic neuropathy, the spinal protein levels of CXCL1, CXCL5, CXCL9, and CXCL12, but not CXCL11 and CXCL13, are upregulated." (PMID 25789329, 2015).
endocrine cancers (1 paper, 2025). "Notably, endocrine cancers displayed the highest frequency of positive correlations with pro-inflammatory chemokine genes, particularly with CCL8, CCL11, CXCL1, CXCL5, and CXCL6, thus indicating a distinct regulatory pattern in this cancer subtype." (PMID 40806276, 2025).
enteroviral infection (1 paper, 2013). "Analysis of the cytokine/chemokine-profile following enteroviral infection with a cytometric bead array and Q-PCR revealed an enhanced secretion of PanGRO (CXCL1, CXCL2 and CXCL3), IL8 and CCL5." (PMID 23305147, 2013).
eosinophilic esophagitis (1 paper, 2016). Eosinophilic esophagitis (EoE) is a chronic, allergic disease of the esophagus characterized clinically by symptoms of esophageal dysfunction (including vomiting, dysphagia, feeding disorders, food impaction and abdominal pain) which persist after treatment with proton pump inhibitors (PPIs). "Besides, IL-13 has been implicated in inflammation and remodeling by inducing chemokines (CCL-3, CCL-4, CCL-5 and CXCL-1), and IL-13 is a direct inducer of both CCL11 and CCL24 in eosinophilic esophagitis." (PMID 27533463, 2016).
eye inflammation (1 paper, 2020). "In addition, KSPGs formed a chemokine gradient to mediate infiltration of neutrophils to the cornea through interaction with CXCL1, indicating the importance of these PG/CXCL1 complexes in the inflammatory response in eye inflammation." (PMID 32296423, 2020).
Farber disease (1 paper, 2023). "Additionally, increased plasma levels of IL6, IL10, IL12, CCL2, CCL3, CXCL1, and VEGF and substantial central nervous system defects have been observed in patients with Farber disease." (PMID 37189685, 2023).
focal segmental glomerulosclerosis (1 paper, 2015). A renal disorder characterized by sclerotic lesions in the glomeruli. "Furthermore, elevated expression of CXCL1 was also reported in glomeruli of patients with focal segmental glomerulosclerosis obtained by laser capture microdissection." (PMID 25816025, 2015).
gallstones (1 paper, 2025). Solid crystalline precipitates in the biliary tract, usually formed in the gallbladder, resulting in the condition of cholelithiasis. "CXCL1 enters the liver via the portal vein and increases the formation of NETs in the liver, thereby accelerating gallstone formation." (PMID 40309357, 2025). "We then established a gallstone mouse model by gavaging C. scindens and subsequently used Robinin to inhibit TLR2 and Reparixin to inhibit CXCL1." (PMID 40309357, 2025).
gastric diseases (1 paper, 2022). "Furthermore, IL-8, CXCL1, and MCP-1 are responsible for monocyte migration to the sites of infection in H.pylori-associated gastric diseases." (PMID 35506423, 2022).
gastroesophageal reflux (1 paper, 2025). "This association may be due to the fact that CXCL1 recruits neutrophils, which produce reactive oxygen species and lipid peroxidation that are mainly involved in the progression of esophageal inflammation caused by gastroesophageal reflux." (PMID 40441226, 2025).
geographic atrophy (1 paper, 2016). "Up-regulation of Ccl2, Cxcl1, Cxcl10, and Cxcl11 are present in all forms of AMD, and the Ccl2/Ccr2 axis is implicated in the pathogenic accumulation of macrophages to the outer retina in models that feature aspects of either CNV or geographic atrophy, such as light damage." (PMID 26911327, 2016).
hemangioendothelioma (1 paper, 2024). A vascular proliferation characterized by the presence of prominent endothelial cells and the formation of vascular channels. "High basal NF-κB activity has been reported in hemangioendothelioma cells, which results in high CXCL1 expression; for this reason, there is a high expression of CXCL1 in clinical samples of this cancer." (PMID 38673949, 2024). "Although CXCL1 is not important in hemangioendothelioma cell proliferation, it does induce cancer cell migration." (PMID 38673949, 2024).
hematoma (1 paper, 2020). A hematoma is a collection of blood from a vascular structure into an extravascular space. "At the fracture site (hematoma), there were no major alteration in levels of CXCL-1, IL-6, and MCP-1 except for MIP-1α that was higher by trend in GRdim compared to wild type mice in the context of combined trauma." (PMID 33679723, 2020).
hemorrhagic fever (1 paper, 2017). An infectious disease caused by certain viruses or bacteria that can damage the walls of tiny blood vessels, making them leak, and can hamper the blood's ability to clot and cause severe, life-threatening illness. "Hemorrhagic fever with renal syndrome cases were characterized by a strong expression of MIF, IL-12p40, IL-3, IL-16, CXCL9, CCL27, CXCL1, and HGF." (PMID 28572804, 2017).
hepatic granuloma (1 paper, 2020). A granuloma located in the liver. "We found that this sensor influences the formation of hepatic granuloma, altering local chemokine (CCL2, CCL3, and CXCL1) and cytokine (IL-5, IL-10, and IL-13) production, macrophage and neutrophil recruitment into the liver, and also is important for promoting collagen deposition." (PMID 32431709, 2020).
hepatitis B (1 paper, 2013). "In contrast, a Chinese research group identified CXCL1 together with thrombin light chain and alpha-fetoprotein as serological biomarkers for HCC in hepatitis B infected patients." (PMID 24260493, 2013).
Hodgkins’ disease (1 paper, 2011). "Furthermore, in Hodgkins’ disease, CXCL1 chemoattraction of inflammatory cells contributes to a complex tumour–host cellular interplay that can result in suppression of cell-mediated cellular immune response and consequently, tumour progression." (PMID 21285972, 2011).
Hypercholesterolemia (1 paper, 2013). An increased concentration of cholesterol in the blood. "An alternative role of CXCR2 in atherogenesis was unveiled by our findings that its ligand CXCL1 mediates mobilization of classical monocytes under hypercholesterolemia." (PMID 23417922, 2013). "Increased CXCL1 levels accompanied by higher expression of its receptor CXCR2 on classical monocytes and inhibition of monocytosis by CXCL1-neutralization indicated a preferential role for the CXCL1/CXCR2 axis in mobilizing classical monocytes during hypercholesterolemia." (PMID 23417922, 2013).
hypercoagulability (1 paper, 2013). "Consistent with this view, hypercoagulability promoted a significant increase in plasma CCL2 and CXCL1 levels." (PMID 23409043, 2013).
hyperreactivity (1 paper, 2022). "Similar experiments demonstrated that neutralization of CXCR2, the receptor for the chemokines CXCL1, CXCL2, granulocyte chemoattract protein 2, and LPS-induced CXC chemokine, prevents RSV-induced airway hyperreactivity but does not alter viral clearance." (PMID 35062301, 2022).
hypertensive heart disease (1 paper, 2025). Abnormal enlargement of the heart resulting from long-standing hypertension. "This study concluded that the inhibition of CXCL1 and/or CXCR2 might be a promising therapeutic approach for treating hypertensive heart diseases." (PMID 40109339, 2025).
idiopathic membranous nephropathy (1 paper, 2021). "Interleukin 6 and CXCL1 have been suggested to be involved in the progression of renal injury in IgA nephritis, while IL-8 levels were associated with poor prognosis in idiopathic membranous nephropathy." (PMID 33800255, 2021).
infectious colitis (1 paper, 2020). A viral or bacterial infectious process affecting the large intestine. "Such host–pathogen interaction at the colonic mucosa resulted in the production of the neutrophil chemoattractant CXCL8 (humans)/CXCL1 (mice) and pathogen clearance, representing a novel endogenous innate cathelicidin defense in the setting of infectious colitis." (PMID 32658599, 2020). "Thus, defective gut defense in cathelicidin-null mice was, at least in part, attributed to a reduced CXCL1-stimulated influx of neutrophils during infectious colitis and, LPS+LL-37 can drive epithelial chemokine responses at concentrations of LL-37 that were below microbicidal or cytotoxic." (PMID 32658599, 2020).
inflammatory breast carcinoma (1 paper, 2025). An advanced, invasive breast adenocarcinoma characterized by the presence of distinct changes in the overlying skin. "Previous studies conveyed that NF-κβ can dramatically increase the expression of many genes in inflammatory breast cancer, including CD40, IL15, COX2, and CXCL1." (PMID 40035822, 2025).
interstitial cystitis (1 paper, 2021). A rare chronic debilitating urogenital disease characterized by urinary frequency, urgency, and pelvic pain. "The core genes (CXCL8, CXCL1, IL6) obtained in this study may be potential biomarkers of interstitial cystitis with guiding significance for clinical treatment." (PMID 33848079, 2021).
Kaposi's sarcoma (1 paper, 2024). A malignant neoplasm characterized by a vascular proliferation which usually contains blunt endothelial cells. "CXCL1 plays an important role in the pathogenesis of Kaposi’s sarcoma." (PMID 38673949, 2024). "As CXCL1 and CXCL8/IL-8 are angiogenic factors, they play an important role in the early stages of Kaposi’s sarcoma, particularly in the development of its angiogenic phenotype." (PMID 38673949, 2024).
laryngeal carcinoma (1 paper, 2024). Carcinoma that arises from the laryngeal epithelium. "For laryngeal cancer, we found CXCL1 (sensitivity = 81.48, specificity = 79.17, ROC Area = 0.8596, threshold = 0.1423) as a strong candidate and IL1b (sensitivity = 75.86, specificity = 72, ROC Area = 0.7462, threshold = 0.1681) as weak candidate biomarker." (PMID 38175424, 2024).
Listeria infection (1 paper, 2023). "It has been shown that Kupffer cell activation and macrophage infiltration in response to Listeria infection is mediated by TLR-2 dependent secretion of Cxcl1 and Ccl2 and that the macrophage infiltration is also stimulated by exogenous Ccl2 and Cxcl1 capabilities." (PMID 36650530, 2023).
liver toxicity (1 paper, 2020). "Higher levels of sTNFRII (P < 0.001), and lower levels of sCD40L (P < 0.001) and CXCL1 (P = 0.01) following one to two fractions of SBRT were noted in patients who developed liver toxicity vs. those who did not." (PMID 32695883, 2020).
lymphadenitis (1 paper, 2023). Acute or chronic inflammation of one or more lymph nodes. "CXCL9/MIG, CCL20, CCL23, CXCL10/IP-10, CXCL1, CXCL2, and CXCL8 significantly declined in our cohort of EPTB (48 TB pleuritis and 57 TB lymphadenitis) patients at both time points." (PMID 36635313, 2023).
meningioma (1 paper, 2023). A generally slow growing tumor attached to the dura mater. "In our study, using a Mendelian randomization approach, we also found that elevated levels of CXCL1 are associated with an increased risk of developing meningiomas." (PMID 37425011, 2023). "Increased expression of CXCL1 is associated with tumor development and progression in meningiomas." (PMID 37425011, 2023). "Based on the results of our MR analysis, which examines 41 cytokines in the largest GWAS datasets available, we were able to draw the relatively more reliable conclusion that elevated levels of circulating TNF-β, CXCL1, and lower levels of IL-9 were associated with a high risk of meningioma." (PMID 37425011, 2023). "The ability of CXCL1 to enhance cell proliferation provides a mechanistic explanation for its involvement in meningioma development." (PMID 37425011, 2023). "Overall, TNF-beta may promote tumor growth and metastasis in meningiomas, while CXCL1 may be involved in tumor invasiveness and resistance to treatment." (PMID 37425011, 2023). "Research has demonstrated that CXCL1 can promote the proliferation of human meningioma cells." (PMID 37425011, 2023).
microtia (1 paper, 2025). "Moreover, we screened 37 genes as potential diagnostic biomarkers for microtia through SVM-RFE and intersected them with 15 hub genes to obtain two specific biomarkers (IL-6 and CXCL1) in microtia." (PMID 40809693, 2025).
mucinous adenocarcinoma (1 paper, 2023). An invasive adenocarcinoma composed of malignant glandular cells which contain intracytoplasmic mucin. "We found that the concentrations of CXCL1 and CEA were higher in patients with adenocarcinoma than in those with mucinous adenocarcinoma, and these differences were significant only when compared to the control group." (PMID 37509572, 2023).
mucositis (1 paper, 2024). Mucositis is inflammation and damage of the mucous membranes lining the mouth and other parts of the gastrointestinal (GI) tract. "Additionally, the study examined markers of neutrophil chemotaxis (chemokine (C-X-C motif) ligand 1 and 8; CXCL1 and CXCL8, respectively), which have previously been independently associated with both mucositis and BSI." (PMID 37919603, 2024).
mycobacterial infection (1 paper, 2017). "Increased levels of chemokines, including CXCL5, CCL5 and CXCL1, were reported in previous mouse mycobacterial infection experiments." (PMID 29228045, 2017).
nasal polyp (1 paper, 2025). "Nasal secretion CXCL-1 (AUC = 0.812), GM-CSF (AUC = 0.813), IgE (AUC = 0.900) and IP-10 (AUC = 0.800) effectively predicted none or less improvement in nasal polyp score." (PMID 39758936, 2025).
necrotizing enterocolitis (1 paper, 2015). Necrotizing enterocolitis (NEC) is a devastating disease that affects mostly the intestine of premature infants. "Mouse studies have showed an association between higher incidence of necrotizing enterocolitis and elevated intestinal expression of CXCL1 mRNA." (PMID 26303932, 2015).
Neonatal sepsis (1 paper, 2025). Systemic inflammatory response to infection in newborn babies. "Other chemokines, including MMP- 10, CCL20, and CXCL1, have also been studied in diagnosing NEC and differentiating it from neonatal sepsis." (PMID 40295408, 2025).
neuropathy (1 paper, 2023). A disorder affecting the nervous system that manifests with pain, tingling, numbness, and/or muscle weakness. "CXCR2 in the spinal cord, which plays an important role in the development of oxaliplatin-induced neuropathy, and its related ligands, CXCL1, 3, and 5, were analyzed together." (PMID 36768178, 2023).
oligodendroglioma (1 paper, 2024). A well-differentiated (WHO grade II), diffusely infiltrating neuroglial tumor, typically located in the cerebral hemispheres. "At the same time, in oligodendrogliomas, the mitogenic properties of CXCL1 may depend on platelet-derived growth factor (PDGF)." (PMID 38673949, 2024). "The highest percentage of tumors with high CXCL1 expression is in oligodendrogliomas." (PMID 38673949, 2024).
osteopetrosis (1 paper, 2024). Osteopetrosis, also known as marble bone disease, is a descriptive term that refers to a group of rare, heritable disorders of the skeleton characterized by increased bone density on radiographs. "Further studies are necessary to clarify the role played by TGF-β and CXCL1 in the development of osteopetrosis in MF." (PMID 39062946, 2024).
osteosclerosis (1 paper, 2024). Abnormally high bone density. "Ruxolinitib, in combination with the antibody against the murine P-selectin RB40.34, was more effective than either of the two drugs alone in reducing CXCL1 content in bone marrow and had some effect on osteosclerosis." (PMID 39062946, 2024).
pertussis (1 paper, 2016). A contagious bacterial respiratory infection caused by Bordetella pertussis. "Our current in vivo study demonstrated that immunization with an OMV-based pertussis vaccine (omvPV) in comparison to wPV elicited reduced concentrations of serum pro-inflammatory cytokines (IL-1α, IL-1β, and IL-6), chemokines (CXCL1 and CXCL10), and G-CSF." (PMID 27905535, 2016).
pleural tumor (1 paper, 2018). "Our experiments using CXCR1- and CXCR2-deficient mice support that pleural tumor cell-secreted CXCL1/PPBP is cardinal for MPE and are in line with a previous study demonstrating increased production of CXCL1 by tumor cells during human MPE development that mobilizes regulatory T cells." (PMID 29445180, 2018).
prion disease (1 paper, 2022). A transmissible disease that is caused by a protein that is able to induce abnormal folding of normal cellular proteins, leading to characteristic spongiform brain changes, which are associated with neuronal loss without an inflammatory response. "As KC is a murine paralog for human CXCL1, it may be suspected that humans with prion diseases have an increase in CXCL1 expression in the brain, although that needs to be confirmed by further research." (PMID 35457023, 2022). "Thus, the main property of CXCL1, which is the effect on neutrophils, does not play an important role in the course of prion diseases." (PMID 35457023, 2022).
prostatic intraepithelial neoplasia (1 paper, 2023). "Macrophage-secreted molecules have also been associated with PCa development, such as C5a, CXCL1, and CCL2, by increasing prostatic intraepithelial neoplasia (PIN) cell proliferation." (PMID 37090711, 2023).
psittacosis (1 paper, 2022). "We found significant upregulated expression of multiple chemokines and receptors (CXCL1, CXCL9, and CXCL10/IP-10) in severe psittacosis cases." (PMID 36119044, 2022).
pulmonary embolism (1 paper, 2013). The obstruction of the pulmonary artery or one of its branches by an embolus, sometimes associated with infarction of the lung. "However, support for a Ca2+-independent role of CXC1 in myocardial dysfunction, as suggested by our study, comes from another report and inhibition of CXCL1 decreases right ventricular failure in a model of pulmonary embolism." (PMID 24047433, 2013).